TERT (telomerase reverse transcriptase)
Diseases named in the same sentence as TERT in open-access papers (continued):
Sharing a sentence is not in itself a finding about the gene and the disease.
melanoma (continued). "In summary, our results demonstrate the possible role of TERT expression in metastasis formation and invasion in melanoma and highlight its role in DNA repair mechanisms across cancer entities." (PMID 37418389, 2023). "Our results demonstrated the diversity of TERT biological activities in melanoma and highlight the therapeutic potential of targeting TERT in these tumors." (PMID 37296851, 2023). "In this study, as an extension to our previous work on head and neck mucosal melanomas, we aimed to investigate the BRAF, NRAS, KIT, TERT and GNAQ/GNA11 mutation status of 15 AMs, as well as their clinicopathologic features." (PMID 35642348, 2023). "•Spitzoid morphology is common in familial melanoma cases from individuals with POT1, TERF2IP, ACD, and TERT germline variants." (PMID 36876055, 2023). "Spitzoid morphology was observed in 77% (23 of 30), 75% (3 of 4), 50% (2 of 4), and 50% (1 of 2) of melanomas from individuals with germline variants in POT1, TERF2IP, ACD, and TERT, respectively." (PMID 36876055, 2023). "TERT overexpressing melanoma cells were also inhibited by 6-thio-dG confirming that TERT contributes to melanoma resistance through its telomerase-dependent as well as independent functions." (PMID 37296851, 2023). "To study the role of TERT in resistance to BRAFi and MEKi in BRAF-mutated melanoma, we overexpressed TERT in the BRAF-mutated melanoma cell line SkMel28, which expressed a low level of TERT due to a mutation at −57 bp in the TERT promoter." (PMID 37296851, 2023). "Mutations consisting of G>A transitions at positions −57, −124 and −146 in the core promoter region of the TERT gene were first reported to occur in nearly 70% of melanoma as well as in different cell lines derived from several cancer types." (PMID 38033865, 2023). "We showed that overexpression of TERT in a V600E-BRAF melanoma cell line drove resistance to BRAF and MEK inhibitors by a mechanism involving the reactivation of the MAPK pathway independently of telomere maintenance." (PMID 37296851, 2023). "A pigmented lesion assay (PLA) is used to non-invasively detect the presence of three genes associated with melanoma (LINC00518, PRAME, and TERT) using adhesive patch testing and has the potential to reduce unnecessary biopsies." (PMID 36579219, 2022). "Cancer-associated TERT promoter mutations (C228T, CC242TT and C250T) were identified in 10/21 (48%) of melanoma samples." (PMID 35494035, 2022). "These methods have been applied recently to discover melanoma predisposition genes such as MITF, TERT and POT1." (PMID 35085295, 2022). "Here, for TERT -146 we converted T to C. The proliferation, migration and invasion of melanoma cells in vitro, and the growth of the tumor in vivo were inhibited." (PMID 35053139, 2022). "For example, cancer-specific TERT promoter mutations can recruit transcription factor GABPA to mediate long-range chromatin interactions, thus activating TERT expression in melanoma." (PMID 35740532, 2022). "We performed single-molecule high-throughput bisulfite amplicon sequencing in 36 heterozygous and 5 homozygous TERT promoter mutant cell lines, derived from melanoma and other cancers (e.g., urothelial, lung, and brain)." (PMID 36011010, 2022). "Thus, hot spot TERT promoter mutations may help distinguish melanoma from nevus." (PMID 35903534, 2022). "To explore the effect of TERT -146 T>C on melanoma cells, we used the NG-ABEmax to edit TERT -146 and screened heterozygotes and homozygotes, as shown in the Sanger sequencing results." (PMID 35053139, 2022). "Using sequencing datasets from 1,970 melanomas, we found that cancers with RB1 pathway mutations, including CDKN2A/p16, have significant co-occurrence of mutations in TERT and TPTE." (PMID 34983823, 2022). "Similar to the clinical melanoma samples, the wild-type cancer cell lines, on average, had significantly higher TERT distal promoter CpG methylation than mutant cell lines (p < 0.05, one-tail Wilcoxon rank sum test)." (PMID 36011010, 2022).
melanoma (continued). "Telomere maintenance genes such as TERT, ACD, POT1 and TERF2IP were associated to melanoma predisposition previously." (PMID 35085295, 2022). "By RT-qPCR (reverse transcription quantitative real-time PCR), all tested melanomas, except for one, expressed TERT, to various levels, while normal skin controls were negative for TERT expression." (PMID 36011010, 2022). "Here, we exploited NG-ABEmax to revert TERT -146 T to -146 C in melanoma, and successfully obtained TERT promoter revertant mutant cells." (PMID 35053139, 2022). "TERT wild-type melanomas were generally more methylated than mutant melanomas at the distal TERT promoter (one side Wilcox rank sum test, p = 0.0053), but these aberrations were not mutually exclusive." (PMID 36011010, 2022). "Given that TERT is one of the most frequently mutated genes in melanoma, the primary goal of our NGS panel design was to reliably detect the three common TERT promoter mutations in ctDNA." (PMID 35494035, 2022). "The seminal papers reporting TPMs in melanoma pointed at an ETS-mediated role on TERT mutant promoter control, but the identification of the specific factors involved in this regulation, particularly in thyroid cancers, has proven not to be straightforward." (PMID 35053525, 2022). "TERT promoter mutations lead to increased TERT expression and telomerase activity and are common in BRAF V600 mutant melanoma." (PMID 35903534, 2022). "Mutations of the CDKN2A carry a high risk of melanoma, together with CDK4, TERT, and POT1 gene mutations." (PMID 35465855, 2022). "Remarkably, in the current study, we found a significant association with the presence of a TERT promoter mutation and non PAM-derived melanoma." (PMID 34071371, 2021). "Pattern B, which includes lung, melanoma, and pancreatic cancer, has a broader genome-wide significant signal overlapping both the TERT (chr5: 1,253,282–1,295,178 bp) and CLPTM1L genes (chr5: 1,317,869–1,345,180 bp)." (PMID 34355204, 2021). "Less common melanoma susceptibly genes include CDKN2A/ARF, CDK4 (cyclin-dependent kinase 4), TERT, MITF (melanocyte inducing transcription factor), BAP1 (BRCA1 associated protein-1), and POT1 (protection of telomeres 1)." (PMID 34440462, 2021). "GV1001 was the first TERT peptide vaccine to be evaluated for treating advanced pancreatic cancer, lung carcinoma, melanoma, and liver carcinoma in clinical trials." (PMID 34947936, 2021). "Other contributors that promote the uncontrolled proliferative capacity of melanoma cells include mutations in the cell cycle regulating genes, CDKN2A and CDK4, as well as promoter region of Telomerase Reverse Transcriptase (TERT)." (PMID 34359771, 2021). "Oral cavity/pharyngeal cancer also showed a bidirectional, positive relationship with melanoma, even though the two PRS share only one pair of variants in LD in TERT-CLPTM1L." (PMID 33579919, 2021). "One recent in vitro study conducted on acral melanoma cells revealed the cytotoxic effects of TERT inhibitors in melanoma cells harboring TERT genomic alterations." (PMID 33741265, 2021). "In the Brazilian population, a study evaluating the prevalence of Germline TERT and MITF mutations in Brazilian Melanoma-Prone Patients showed an allele frequency of 0.004 in control group (1 out of 125 healthy controls) and 0,01 in melanoma patients’ cohort." (PMID 34289891, 2021). "Several large-scale sequencing studies in melanoma identified significantly mutated melanoma genes, such as NF), ARID2, TERT or RAC beside the well-established oncogenes including NRAS, BRAF or KIT." (PMID 33578810, 2021).
melanoma (continued). "We first looked at an extended list of high-risk genes predisposing to melanoma (ACD, CDKN2A, CDK4, POT1, TERF2IP, and TERT) or RCC (CDKN2B, FH, FLCN, MET, PBRM1, PTEN, SDHs, TSCs, and VHL) or both (BAP1 and MITF)." (PMID 34067022, 2021). "TERT promoter mutations and CDKN2A are also frequently found in these melanomas, and KIT mutations are found in a subset of cases." (PMID 34571969, 2021). "In this study, we evaluated the effect of the two TERT hotspots on the outcome of melanoma patients treated with MAPKi." (PMID 32290374, 2020). "Second, Wnt effector, β-catenin, can interact with telomerase reverse transcriptase (TERT) to control age-related melanoma progression." (PMID 33373316, 2020). "TERTp methylation was positively correlated with chromatin accessibility and TERT mRNA expression in 8 melanoma cell lines." (PMID 32267900, 2020). "Examples are mutations in the DNA repair gene BRCA2 in melanoma or in different stage IV cancers alterations in NOTCH, TERT, and NF1." (PMID 33353145, 2020). "In spite of the high promoter methylation fraction in wild-type (WT) samples, TERT mRNA was only expressed in the melanoma cell lines with either high methylation or intermediate methylation in combination with TERT mutations." (PMID 32267900, 2020). "Therefore, male melanoma patients with TERT mutation may benefit from immunotherapy." (PMID 32915164, 2020). "We and others established the existence of CD4 Th1 cell specific for different TERT epitopes in several cancers including leukemia, lung, colon, melanoma, renal, and liver cancers." (PMID 32630460, 2020). "Nevertheless, in melanoma cell lines, a dramatic decline in TERT transcription and telomerase activity was observed after short-term exposure to MAPKi, regardless of TERTprom mutation." (PMID 32290374, 2020). "The effect of chromatin accessibility in TERT expression was evaluated in a subset of cultured melanoma cell lines." (PMID 32267900, 2020). "An implementation study employing a customized Ampliseq NGS panel including 35 genes reported BRAF, TERT and NRAS as the most prevalent mutated genes in a set of 100 primary melanoma samples." (PMID 33083132, 2020). "Oncogenomic studies indicate that somatic CNV of some genes is involved in melanoma progressions, such as mutated gene amplifications in CCND1, CDK4, and TERT, of which the CNV status also has been reported in Chinese melanomas." (PMID 32083130, 2020). "The same study showed that TERT ectopic expression alone was sufficient to rescue the growth of melanoma cells expressing BRAF-targeting short hairpin RNA." (PMID 33024276, 2020). "Of the regions in TERT-CLPTM1L, one was associated with breast cancer and melanoma, and the other was associated with melanoma and cervical and pancreatic cancers." (PMID 32887889, 2020). "GV1001 was the first TERT peptide vaccine to be evaluated in clinical trials against advanced pancreatic cancer, lung carcinoma, melanoma, and liver carcinoma." (PMID 32674474, 2020). "In our study we used ddPCR to investigate the clinical validity of ctDNA measurements in melanoma patients treated with bevacizumab monotherapy by quantifying BRAF, NRAS and TERT promoter mutations in plasma." (PMID 31767937, 2019). "Accordingly, with respect to BRAFV600E-mutated melanoma, both phosphorylation of ETS1 and upregulation of GABPB via Fos have been shown to link oncogenic BRAF signaling to activation of the mutant TERT promoter." (PMID 31391125, 2019). "For example, patient MM475 had multiple recognized melanoma driver mutations including BRAF p.V600R, RAC1 p.P29S, MAP2K1 p.P124S, TERT C228T, and DPH3 C8T." (PMID 30312528, 2019).
melanoma (continued). "We performed a retrospective analysis of plasma ctDNA using droplet digital PCR (ddPCR) in 30 primary melanoma patients with tumors harboring BRAF, NRAS or TERT promoter mutations." (PMID 30719207, 2019). "Accordingly, a recent study in melanoma has shown that the C228T variant, the predominant mutation detected in our panel, is more efficiently activated by ETS1 as compared to the other TERT promoter mutations." (PMID 31391125, 2019). "TERT promoter variations were found in 33% of primary melanomas and 85% of metastatic lesions, but were distributed over several different positions." (PMID 30987166, 2019). "To determine the therapeutic value of exploiting melanoma cell dependency on TERT, we used the nucleoside analog 6-thio-dG-2′-deoxyguanosie (6-thio-dG)." (PMID 29695835, 2018). "To determine the dependency of NRAS-mutant melanomas on TERT, we evaluated the effect of TERT silencing in these cells." (PMID 29695835, 2018). "We next sought to clarify the requirement for the catalytic activity of TERT for the pro-survival function of this protein in NRAS-mutant melanoma." (PMID 29695835, 2018). "Variations at TERT gene promoter in melanoma patients generate binding sites for Ets/TCF transcription factors and have “effect on DNA interaction” (VariO:0230)." (PMID 30591019, 2018). "Consistent with previous reports indicating that the RAS/MEK signaling pathway regulates TERT expression, treatment of NRAS-mutant melanoma cells with the MEK inhibitor trametinib downregulated TERT mRNA levels." (PMID 29695835, 2018). "Variations at two major TERT (telomerase reverse transcriptase) gene promoter sites are frequent in melanoma patients and generate binding sites for Ets/TCF transcription factors." (PMID 30591019, 2018). "Among the 9 primary melanoma samples which presented mutations at codon 61 of NRAS gene, 7 were successfully amplified for TERT: 4 (57%) showed mutations in TERT promoter and 6 (86%) presented the –245T>C polymorphism." (PMID 29464027, 2018). "Our studies support the notion that NRAS-mutant melanoma is a prime candidate for TERT-based therapeutic approaches." (PMID 29695835, 2018). "We investigated the consequences of NRAS blockade in NRAS-mutant melanoma and show that decreased expression of the telomerase catalytic subunit, TERT, is a major consequence." (PMID 29695835, 2018). "Here we used NRAS-mutant melanoma as a treatment refractory model to investigate the therapeutic value of exploiting melanoma’s addiction to TERT, and activation of adaptive mechanisms limiting the effects of TERT-based approaches." (PMID 29695835, 2018). "Another independent study on the TERT promoter of melanomas showed that 125 of the 168 human cancer cell lines screened contain the same somatic mutations." (PMID 29922517, 2018). "Together, our results indicate that therapeutic approaches exploiting melanoma cell addiction to TERT, and combating the ability of NRAS-mutant melanoma to offset oxidative stress, would render cancer cells vulnerable to drug-induced cell death." (PMID 29695835, 2018). "Considering the total primary melanomas, we observed that BRAF mutation was concomitant in 19 out of 76 (25%) of samples with TERT promoter mutations and in 41 out of 62 (66%) with p16 loss of expression." (PMID 29464027, 2018). "Mutations in the TERT gene promoter are found in many cancers, including melanoma, where it has been reported that UVR signature mutations are seen in 33% of primary melanomas and in 85% of melanoma metastases." (PMID 29946532, 2018). "In particular, the most frequent somatic mutations in cutaneous melanoma like those in the TERT promoter and BRAF/NRAS reportedly associate with poor disease-free and melanoma-specific survival." (PMID 30026606, 2018).
melanoma (continued). "TERT mRNA expression level was significantly higher in cases of conventional melanoma than in nevoid or spitzoid samples." (PMID 28378855, 2017). "Zidovudine or Azidothymidine is a TERT inhibitor that has shown significant melanoma tumor reductions in mouse models." (PMID 37133296, 2017). "An important role of RAS-ERK signaling is in the maintenance of an active chromatin state at mutant TERT promoters, facilitating the recruitment of RNA polymerase II that activates TERT transcription in BRAF-mutant melanoma cells." (PMID 29156643, 2017). "TERT mRNA levels in the conventional melanomas were 4- to 300-fold (median, 69-fold) above the reference sample (spitzoid melanoma ID#20), while two of these samples (ID#2 and #22) had extremely high expression levels as compared with the other samples." (PMID 28378855, 2017). "Availability of a reliable anti-TERT antibody has enabled us to investigate this by TERT immunohistochemistry (IHC) in nevi and melanomas." (PMID 29262649, 2017). "The TERT/CLPTM1L region is frequently identified by GWAS for conferring tumor risk for many tumor types, including pancreatic, lung, melanoma, and bladder cancers (see refs 16, 17 for meta-analyses)." (PMID 28781888, 2017). "The TERT promoter mutation results in a de novo ETS-binding site and occurs in 55% of melanoma samples." (PMID 28854983, 2017). "Fluorescence in situ hybridization revealed that 2 of 8 conventional melanomas tested harbored rearrangements involving the TERT locus." (PMID 28378855, 2017). "The number of TERT promoter copies per mL of plasma detected in the melanoma patient cohort varied from 11.2 to 176 copies per mL." (PMID 29108273, 2017). "Of note, a relatively high level of TERT mRNA was measured in a primary melanoma which later developed distant metastasis, despite the fact that the tumor harbored a wild-type TERT promoter and was initially diagnosed as stage I disease (ID #14)." (PMID 28378855, 2017). "The co-existence of TERT promoter mutations with BRAF or NRAS mutations (in 55% of cases) is associated with poor disease-free and melanoma-specific survival." (PMID 29108273, 2017). "The level of TERT mRNA expression was highly variable among the conventional melanomas and low or undetectable in the nevoid and spitzoid melanomas." (PMID 28378855, 2017). "In this study, we assessed the presence of SDHD promoter mutations and SDHD protein expression in CM, OM and in melanoma cell lines, in which we already determined BRAF, NRAS, GNAQ and TERT promoter mutational status." (PMID 28662141, 2017). "ETS1 has been implicated as a predominant factor activating mutant TERT promoters in melanoma, but previous studies have reached differing conclusions on ETS1 expression relative to melanoma progression." (PMID 29262649, 2017). "The results also included 10 SNPs previously identified for melanoma risk reported at MC1R (2 SNPs), MX2, TERT/CLPTM1L, PLA2G6, CASP8, ACTRT3, ASIP, CDC91L1, and ARNT/SETDB1/LASS2ANXA9/MCL1/CTSK." (PMID 27993549, 2017). "Here, we show that frequently recurring promoter mutations in melanoma occur almost exclusively at cytosines flanked by a distinct sequence signature, TTCCG, with TERT as a notable exception." (PMID 28489852, 2017). "We used A375P melanoma cells, Hermes 3A TERT/CDK4-immortalized human melanocytes, and SGML-2 normal human melanocytes." (PMID 29262649, 2017). "In contrast, in pediatric melanomas arising in congenital nevi, NRASQ61 mutation, and TERT promoter mutation were observed." (PMID 29156643, 2017). "In our primary melanoma series, BRAF mutations were the most prevalent (50%) followed by TERT promoter mutations (33%)." (PMID 28356599, 2017).